IL6 (interleukin 6)
Diseases named in the same sentence as IL6 in open-access papers (continued):
Sharing a sentence is not in itself a finding about the gene and the disease.
colitis (continued). "Our immunohistochemical results showed that HBD reduced the expression of JAK2 and P-STAT3 associated with the IL-6/STAT3 signaling pathway and inhibited the formation of tumor cells in colitis-associated colon cancer." (PMID 30832202, 2019). "To understand the mechanism that underlies the alleviation of DSS-induced colitis in mice after treatment with EPS-1, we examined the levels of Th1 pro-inflammatory (TNF-α, IL-6, and IFN-γ) and anti-inflammatory (IL-4 and IL-10) in colon tissues." (PMID 30708992, 2019). "Progressive release of cytokines IFN-γ and IL-6 from inflamed colon, produced by T cells and macrophages was also shown to be correlated with development of colitis." (PMID 30708992, 2019). "In tissue from patients with IRAE-induced colitis, the gene with the greatest degree of differential upregulation from normal colonic tissue was IL-6." (PMID 31730012, 2019). "Recently, we observed after colitis development and C. glabrata challenge a high production of IL-6 and IL-1β, which are highly important in the recruitment of neutrophils and macrophages into the inflammatory site." (PMID 30646601, 2019). "It was found that treatment with JGT or 5-aminosalicylic acid (5-ASA) alleviated the severity of colitis symptoms by suppressing inflammatory cytokine levels of IL-6, IL-12, and IFN-γ." (PMID 31615012, 2019). "Lower circulating IL-6 was significantly correlated with higher incidences of colitis-related irAEs." (PMID 31192215, 2019). "IL-6 levels at doses of 0.1 and 1mg/kg of dizocilpine tend to be declined compared to colitis control group." (PMID 32641944, 2019). "In the present study, there was a significant decrease in the expression of IL-6 following rBmaCys-administration in DSS-induced colitis mice." (PMID 31683524, 2019). "Taken together, these results suggest that the side chains of pectin not only augment prebiotic effects but also directly regulate IL-6 production from intestinal host cells in a microbiota-independent fashion to attenuate colitis." (PMID 31921214, 2019). "The expression of IL-6 and IL-17 mRNA was significantly elevated in tissues of mice with colitis from 1 to 4 weeks after DSS treatment." (PMID 31780871, 2019). "GA attenuates experimental colitis by suppressing IL-6, IL-1β, TNF-α, IL-17 and IFN-γ production and inhibiting p65-NF-κB and IL-6/p-STAT3 (Y705) activation." (PMID 31026283, 2019). "In the rat colitis model, IL-1β, IL-6, and IL-17 have been recognized as important proinflammatory cytokines in the course of UC, and overexpression of these cytokines is related to activation of the NF-κB and MAPK pathways in colonic tissue." (PMID 31920656, 2019). "In the same manner, IL-6 level was significantly increased in the colitis control group compared to the Sham group (P < 0.001)." (PMID 32641944, 2019). "We found that severe colitis in aHPD-fed RAG2−/− mice is associated with high levels of homeostatic cytokine IL-33 and pro-inflammatory cytokines TNF-α and IL-6." (PMID 31105710, 2019). "Collectively, these results provide evidence that orange pectin ameliorates colitis at least in part by attenuating IL-6 production in colon." (PMID 31921214, 2019). "Tussilagone, a molecule able to inhibit NF-κB activation and to induce Nrf2, reduced the main markers of murine colitis induced by DSS (i.e., TNF-α and IL-6) suggesting its potential role in the treatment of colitis." (PMID 31434263, 2019). "Our results showed that colitis mice had lower levels of IL-6 and TNF-α after Safranal treatment than 3.5% DSS-treated mice, suggesting that Safranal alleviated the severity of colitis by decreasing IL-6 and TNF-α in colon tissue." (PMID 31736758, 2019). "Another study showed that lower circulating IL-6, as well as IL-8, was significantly correlated with higher incidences of colitis-related irAEs." (PMID 31192215, 2019).
colitis (continued). "The role of ATP was found to be associated with Th17 cells differentiation, as ATP found to enhance the expression of TGF-β, IL-6, IL-23p19, and thus enhanced Th17 cell generation and exacerbated T-cell-mediated colitis in mouse model." (PMID 31164892, 2019). "Significantly lower concentrations of inflammatory cytokines of innate immunity (p < 0.05 for IL-1β, TNF-α, and IL-6) were observed in serum samples of DSS-treated Gal-3−/− mice at the end of induction phase of colitis." (PMID 31336879, 2019). "Consistently, we observed an elevation of these cytokines, including TNF-α, IL-1β, and IL-6, p-IκB, NFκB p65, p22-phox, gp91-phox, and Keap1 in colitis mice." (PMID 31827675, 2019). "NFATC2 is involved in colitis by controlling mucosal T cell activation in an IL-6-dependent manner and seems to be a potential therapeutic target for UC." (PMID 31249629, 2019). "IL-6 promotes a protective effect in some inflammatory diseases, such as inflammatory bone destruction and dextran sodium sulphate-induced colitis." (PMID 31600945, 2019). "Lactobacillus plantarum CAU1055 had significantly reduced levels of TNF-α, and IL-6 in a dextran sulfate sodium-induced colitis animal model." (PMID 31921049, 2019). "Knowing that intestinal macrophages have been reported to supply IL-6 and raise the inflammatory response in DSS-induced colitis, these results indicated that orange pectin regulates IL-6 production in colon, thereby attenuating the inflammatory response." (PMID 31921214, 2019). "Previous studies reported that neutralization of IL-6 improves DSS-induced colitis, thus we assumed that orange pectin exerted stronger inhibitory effect on IL-6 production in macrophages than citrus pectin." (PMID 31921214, 2019). "Secretion of IL-6 strongly increased during DSS-induced colitis and reached levels of approximately 40 pg/ml on day 10 in mice of both genotypes." (PMID 29324769, 2018). "Pro-inflammatory cytokines, such as TNF-α, IL-1β and IL-6, play important roles in colitis development." (PMID 29495327, 2018). "We provide evidence that F. hepatica EVs can prevent DSS-induced colitis by down regulating pro-inflammatory cytokines like TNFα, IL-6, and IL17A, as well as suppressing MAPK/NF-κB signaling pathways." (PMID 29875750, 2018). "Consistent with these prior findings, it should be noted that IL-6 was one of the cytokines that we found to be further increased in Smox−/− mice during DSS colitis." (PMID 29922289, 2018). "Consistent with previous reports, we observed that TNBS-induced colitis invariably promoted inflammation in the colon with elevated levels of IL-1β, IL-6, TNF-α and an increased expression of JAK2, STAT3, and p-STAT3." (PMID 30042683, 2018). "EtOH significantly elevated IL-6 mRNA in colonic mucosa, and DSS-induced colitis elevated mRNA for IL-1β, TNFα and IL-6." (PMID 30389960, 2018). "TLR4/NF-κB and IL-6/JAK2/STAT3 signal pathways were investigated to evaluate the alleviation of CP on the TNBS-induced colitis." (PMID 30042683, 2018). "In the present study, we found that SAA-administrated colitis rats showed decreased expression of the pro-inflammatory cytokines IL-1β, IL-6, and MCP-1." (PMID 29921812, 2018). "Mice engineered to lack components of the serotonergic system have revealed 5-HTs participation in gut disease: TPH1−/− mice exhibited reduced severity of chemical-induced colitis and an accompanying reduction in IL-1β, IL-6, and TNF-α." (PMID 30177522, 2018). "The pro‐inflammatory cytokines (IL1A, IL1B and IL‐6), neutrophils and bacterial infiltration were significantly increased in CD11c‐Cre+Rab32f/f mice with colitis induced by DSS." (PMID 30338217, 2018). "Plasma levels of TNFα, IL-1β and IL-6 in the plasma were significantly increased by EtOH feeding and colitis." (PMID 30389960, 2018).
colitis (continued). "Obvious hyperemia and inflammatory cells infiltration were found in the colitis control groups accompanied with higher proinflammatory cytokines (IL-6 and TNF-α) and lower anti-inflammatory cytokines (IL-4 and IL-10)." (PMID 29785192, 2018). "Mirroring this improvement in colitis, Rag2−/−hLrh1IEC-TG animals showed a decreased inflammatory cytokine profile, with lower intestinal expression of TNFα, IL-1β, and IL-6, and a corresponding increase in the anti-inflammatory cytokine IL-10." (PMID 30305617, 2018). "The level and expression of TNF-α and IL-6 is increased in several models of colitis, including in IBD patients." (PMID 30024891, 2018). "TNF-α, IL-6, NF-κβ, and STAT3 turned out to be associated with intestinal inflammation, leading to a predisposition to colorectal cancer associated with colitis." (PMID 30545135, 2018). "In colitis rats, the observed up-regulation of pro-inflammatory cytokines including IL-6 was ameliorated by CP, meanwhile, phosphorylation of Stat3 and JAK2 was blocked." (PMID 30042683, 2018). "In a murine T-cell transfer or TNBS model of colitis, expression of IL-1β, IL-6, tumor necrosis factor alpha (TNF-α), and IL-10, which are involved in inflammation, was regulated by B. fragilis." (PMID 30429227, 2018). "Mice lacking TPH-2 (neuronally restricted expression) exhibit increased severity of disease accompanied by elevated TNF-α, IL-1β, and IL-6 levels during experimental colitis compared with wild-type mice." (PMID 30177522, 2018). "Elevated TNFα, IL-6 and IL-12 levels have been reported to be reduced by Naltrexone in chemically induced mouse colitis models." (PMID 29523156, 2018). "To investigate changes in pro-inflammatory cytokine levels in a DSS-induced colitis model, we measured IL-1β, IL-6, and TNF-α levels at the mRNA (RT-PCR) and protein (ELISA) levels in the colon." (PMID 29610929, 2018). "Increasing productions of proinflammatory cytokine are associated with DSS-induced colitis, which produce various proinflammatory cytokines, including TNF-α, IFN-γ, IL-6, IL-8, IL-12, and IL-17." (PMID 30402509, 2018). "The results provided further evidences of the effects of CP on suppression of colitis and indicated the key role of IL-6/JAK2/STAT3 pathway as relevant targets of CP." (PMID 30042683, 2018). "We found that metformin ameliorated the induction of colitis and reduced the levels of pro‐inflammatory cytokines IL‐6, TNF‐a and IL‐1β." (PMID 29148173, 2018). "The results indicated that the infusion of fAT-MSCs had inhibitory effects on the expression of TNF-α, IL-1β, IFN-γ, and IL-6, which are classically associated with DSS-induced colitis, in the colonic tissue." (PMID 30453939, 2018). "Out results demonstrated that the levels of TNF-α, IL-1β, and IL-6 were markedly downregulated in the colonic LP in colitis mice with GLP treatment." (PMID 29888292, 2018). "In fact, pro-inflammatory cytokines (TNF, IL-1β and IL-6) contributed to tissue destruction and colitis perpetuation." (PMID 30592734, 2018). "The detected concentrations of the two cytokines TNF-α and IL-6 showed that their levels decreased after TRYP treatment of the colitis." (PMID 29724065, 2018). "When analyzing systemic IL-6 secretion in DSS-induced colitis, we found a massive increase at the peak of the disease as well." (PMID 29324769, 2018). "EtOH feeding or DSS-induced colitis significantly elevated mRNA for IL-1β, TNFα and IL-6 genes in ileal mucosa." (PMID 30389960, 2018). "Cystatin from the nematode parasite Ascaris lumbricoides reduces inflammation in a mouse model of DSS-induced colitis by increasing the expression of IL-10, TGFβ with simultaneous reduction of IL-6 and TNFα." (PMID 29141050, 2017). "Using a mouse model of AOM-DSS-induced colitis-associated CRC, IL-6 was also shown to be a strong promoter of colonic tumor growth." (PMID 28632155, 2017).
colitis (continued). "In contrast, H. polygyrus pre-infection in the RAG2-/- T cell transfer colitis model seems to induce IL-6 and CXCL1 in the colon in the same manner as in the DSS model." (PMID 28938014, 2017). "L. reuteri can suppress intestinal inflammation in a trinitrobenzene sulfonic acid-induced mouse colitis model via downregulation of gene expression of mucosal cytokine IL-6 and IL-1β in the colon." (PMID 28943876, 2017). "In the sedentary group fed a SD, the plasma TNF-α, MCP-1, IL-6 and IL-13 were negligible but in the mice with colitis, a significant increase in the plasma levels of these cytokines was observed (p < 0.05)." (PMID 28425943, 2017). "PLP treatment ameliorated colitis in IL-10−/− mice due to a reduction in colonic TNFα, IL-6, IFNγ, COX-2 and nitric oxide synthase (iNOS) expression and modulation of the chemotactic lipid S1P." (PMID 28804483, 2017). "It is well known that the increased pro‐inflammatory cytokines (TNF-α, IL-1β and IL-6) observed in our model of colitis amplify the inflammatory cascade and result in intestinal tissue damage in patients with UC." (PMID 28270147, 2017). "SAMe and MTA inhibited IL-6/STAT3 signaling and lowered tumor burden in a colitis-associated cancer model." (PMID 29108270, 2017). "In line with the morphological appearance of colitis in the knockout mice, the expression of proinflammatory cytokines and chemokines, including IL6, IL1β, Cxcl1, and Ccl2, are dramatically increased in the colonic epithelial cells of the knockout mice." (PMID 28296893, 2017). "In colonic tumorigenesis, the inflammatory cells contributed to the colitis by generating proinflammatory cytokines, such as IL-1α, IL-2, IL-6, TNF-α, INF-γ." (PMID 29162930, 2017). "IL-6−/− mice exhibited a more severe DSS-induced colitis, elevated apoptosis, and decreased IEC proliferation, similar to mice with IEC-specific deletion of STAT3." (PMID 28852270, 2017). "Inflammation-associated mouse models of colon cancer show that IL-17A-/- mice exhibit milder sign of colitis and tumor growth and reduced levels of the pro-inflammatory cytokines IL-6 and TNF." (PMID 28881611, 2017). "In fact, an increase in cytokines, including the ‘cytokine triumvirate’ of TNF-α, IL-6 and IL-13, has been recently proposed to play a role in the progression of experimental colitis and human IBD." (PMID 28425943, 2017). "The analysis of blood samples collected from the DSS-treated mice showed an increase of IL-6 level of 194% in colitis-induced mice compared to unexposed mice." (PMID 28770521, 2017). "Our results demonstrate that experimental colitis induces eWAT lipolysis via an IL-6/FGF21-mediated signaling pathway." (PMID 28584524, 2017). "Inhibition of CSF-1 suppressed DSS-induced colitis due to diminished immune cell infiltration of T cells and macrophages in colon tissue and reduction of TNFα, IL-1β and IL-6 levels." (PMID 29261815, 2017). "In summary, we conclude that H. polygyrus infection prior to DSS-induced colitis further enhances the inflammatory response in the colon based on enhanced IL-6 and CXCL1 expression and increased CD4+ T cell activation." (PMID 28938014, 2017). "We observed that the colonic levels of TNF-α and IL-6 in the DSS-induced colitis mice were markedly decreased by ULP-SeNPs, as measured by ELISA." (PMID 28270147, 2017). "It has been earlier shown that S1P4 deficient dendritic cells show reduced IL-6 production in vitro and that S1P4 deficient mice had lower IL-6 levels in a colitis model in vivo." (PMID 28367448, 2017). "Clinical studies and animal experiments have demonstrated a crucial role of proinflammatory pathways, especially the NF-κB, IL-6/STAT3, COX-2/PGE2, and IL-23/Th17 signaling pathways, in the pathogenesis of colitis-associated CRC." (PMID 28852270, 2017). "Elevated levels of IL-6 were found in chronic inflammatory diseases such as arthritis and colitis suggesting importance of the cytokine as a marker for chronic inflammatory diseases." (PMID 28955792, 2017).
colitis (continued). "The observed clinical and histopathological improvement of colitis upon EPO or cibinetide treatment was also associated with reduced levels of nitrite, TNF, IL-1ß, IL-6, IL-12p70, IL-23, IFN-γ and IL-17A in supernatants of colonic organ cultures." (PMID 29026145, 2017). "In this study, we demonstrated that IFN-γ, IL-12, TNF-α, and IL-6 increase in DSS-induced colitis mice." (PMID 28587089, 2017). "Our results clearly underline that H. polygyrus infection mediated colonic IL-6 and CXCL1 release facilitates aggravation of DSS-induced colitis." (PMID 28938014, 2017). "The colitis mice given a neutralizing S100a9 antibody produced less inflammatory cytokines, such as Tnfα, Il1β, Il6, Il17a, Ifnγ, and Il12a, all of them are master regulators of inflammation and tumorigenesis." (PMID 29326691, 2017). "We show that ONX 0914 treatment reduces IL-6 levels in the early acute colitis phase as well as in later stages of tumor progression." (PMID 28881611, 2017). "Similar results in a model of experimental colitis using gp130 (757 F/F) mice supports the notion that gp130 is a pivotal molecule acting downstream of IL6 to more specifically control macrophage fate and tissue repair." (PMID 28645275, 2017). "Monocytes and macrophages regulate gut inflammation and the majority of tissue infiltrating cells following reactivation of quiescence colitis are M1 macrophage and are the main source of IL-6, IL-1β, and TNF- α." (PMID 28871257, 2017). "We confirmed that reactivation of colitis significantly increased colonic level of pro-inflammatory cytokines IL-6, IL-1β, and TNF- α and decreased level of colonic anti-inflammatory cytokine TGF-β, but IL-10 levels were not affected." (PMID 28871257, 2017). "To examine the effects of MALT1 inhibitors on the cytokine expression in acute DSS colitis model, we measured the levels of IL-1β, IL-6, TNF, IFN-γ, IL-17A and IL-18 in colons of mice following induction of colitis and treatments with MALT1 inhibitors." (PMID 27105502, 2016). "This is consistent with the pro-inflammatory role of IL6 in the gut, as illustrated by Hegazy and El-Bedewy, who ameliorated colitis in vitro by down-regulating IL6." (PMID 27250867, 2016). "In IL-6 (−/−) mice, the induction of acute colitis using DSS significantly inhibited the inflammatory response in the colon and decreased body weight loss compared with WT mice." (PMID 27980357, 2016). "IL-1β, IL-6 and TNF-α are all implicated in increasing the severity and duration of colitis in both mouse models and human patients." (PMID 26998523, 2016). "In this study, Grim19 inhibited DSS induced colitis progression and weight loss in mice by downregulating the production of STAT3 and proinflammatory cytokines, including TNF-α and IL-6, in colonic inflammation." (PMID 27258062, 2016). "In our study we found a strong correlation between HIF-1α and IL-6 mRNA levels suggesting involvement of HIF-1α in transcriptional regulation of IL-6 gene during colonic inflammation and HBO2." (PMID 27656047, 2016). "The increase in lactate concentration in colon promoted protective effects against TNBS-induced colitis preventing histopathological damage, as well as bacterial translocation and rise of IL-6 levels in serum." (PMID 28082985, 2016). "Acer3−/− mice that survived DSS treatment showed more severe colitis, as evidenced by a greater colon shortening, higher levels of inflammatory cytokines (Il-1β, Il-6, Il-23a and Tnf-α), higher MPO activity and more severe pathological manifestations." (PMID 26938296, 2016). "In a prepubertal rat model of colitis with plasma IL-6 elevation, a comparison with healthy rats fed with the same diet to eliminate differences due to undernutrition showed that inflammation explained 30%-40% of growth retardation." (PMID 27636201, 2016).